ZNF556 (zinc finger protein 556)
Description:
May be involved in transcriptional regulation.
Synonyms: FLJ11637
Tractability: No criterion of Open Targets' tractability assessment is met for any kind of drug.
Gene: Protein-coding gene on chromosome 19 (2,867,335 to 2,883,445, forward strand). Ensembl gene ENSG00000172000.
Subcellular location: Nucleus
Subcellular location (Human Protein Atlas): Nucleoplasm
Pathways (Reactome):
Gene expression (Transcription): Generic Transcription Pathway
Gene Ontology:
Molecular function: DNA-binding transcription factor activity, RNA polymerase II-specific; RNA polymerase II transcription regulatory region sequence-specific DNA binding
Biological process: regulation of transcription by RNA polymerase II; regulation of DNA-templated transcription
Cellular component: nucleus
Genetic constraint (gnomAD): Loss-of-function variants: 12 observed, 13.6 expected, observed/expected ratio (o/e) 0.88, 90% interval 0.56 to 1.43. The upper end of that interval is the gene's LOEUF score, 1.43, which puts it in group 5 of 6, group 1 being the genes least tolerant of losing a copy. Missense variants: 633 observed, 593.88 expected, observed/expected ratio (o/e) 1.07, 90% interval 1 to 1.14. Synonymous variants: 229 observed, 218.05 expected, observed/expected ratio (o/e) 1.05, 90% interval 0.94 to 1.17.
Homologues: Orthologues: chimpanzee ZNF556 (98% identical), macaque ZNF556 (90% identical), dog ZNF556 (61% identical), mouse Zfp78 (37% identical), Drosophila melanogaster CG3281 (22% identical), Drosophila melanogaster CG2712 (22% identical), Drosophila melanogaster Phs (21% identical). Paralogues in human: ZNF555 (43% identical), ZNF77 (39% identical), ZNF69 (39% identical), ZNF266 (38% identical), ZFP90 (38% identical), ZNF20 (38% identical), ZNF440 (38% identical), ZNF599 (38% identical), ZNF778 (38% identical), ZNF439 (37% identical), ZNF805 (37% identical), ZFP37 (36% identical), and 50 more.
Diseases named in the same sentence as ZNF556 in open-access papers:
ZNF556 is named in the same sentence as 4 diseases in open-access papers, as found by Europe PMC text mining. Sharing a sentence is not in itself a finding about the gene and the disease. The quoted sentences say what the papers report.
colon cancer (3 papers, 2020 to 2022). "SOX11, CRISP3, KIF18B, and MELK expression levels have also been found to be positively correlated with poor prostate cancer patient prognostic outcomes, while ZNF556 has been associated with poor colon cancer patient prognosis." (PMID 36245556, 2022). "ZNF556, as a colon cancer biomarker, has been demonstrated to possess a robust predictive ability, which validates the results of this study." (PMID 36072412, 2022). "Therefore, our study provided new insight on potential relationships between overexpression of ZNF556 and the development of colon cancer." (PMID 32957968, 2020).
liver cancer (1 paper, 2024). An epithelial or non-epithelial malignant neoplasm that arises from the liver. "ZNF556 is also specifically expressed in cerebellum, ovaries, HepG2 (liver cancer cell line), and testes (top)." (PMID 38390894, 2024).
ZNF556 also shares sentences with these, for which no sentence is quoted: cancer (1 paper); prostate carcinoma (1).